TNF (tumor necrosis factor)
Diseases named in the same sentence as TNF in open-access papers (continued):
Sharing a sentence is not in itself a finding about the gene and the disease.
rheumatoid arthritis (continued). "Etanercept (Enbrel) is a recombinant dimer of human soluble TNFRII linked by the constant Fc portion of human immunoglobulin 1 (IgG1) and was the first anti-TNF drug to be approved for the treatment of rheumatoid arthritis by the US Food and Drug Administration." (PMID 31076648, 2019). "Genistein was also shown to suppress the expression of IL-1β, IL-6, and TNF-α in the serum, which indicates that it could have the potential to improve symptoms of rheumatoid arthritis in rats." (PMID 31137797, 2019). "Furthermore, ERK-1/2 pathway is activated by IL-18bPa, which decreases the biological activity of IL-18 induced by TNF-α in rheumatoid arthritis synovial fibroblasts." (PMID 31661546, 2019). "Commonly used mouse models of rheumatoid arthritis include TNF-α transgenic mice and K/B × N mice." (PMID 30863410, 2019). "Moreover, cytokines produced in innate immune responses, such as TNFα, IL-6 and IL-1β are found at comparable levels in rheumatoid arthritis joint tissues, early OA and end-stage disease synovium." (PMID 31182934, 2019). "The importance of TNF in inflammation has been highlighted by the efficacy of anti-TNF antibodies or the administration of soluble TNF receptors to control disease activity in rheumatoid arthritis and other inflammatory conditions." (PMID 31480433, 2019). "The pathway analysis results showed that up-DEGs were enriched in proteoglycans in cytokine-cytokine receptor interaction, chemokine signaling pathway, rheumatoid arthritis, and TNF signaling pathway, whereas down-DEGs were enriched in the PPAR signaling pathway and AMPK signaling pathway." (PMID 31139654, 2019). "Importantly, TNF-alpha is a crucial target in the medical management of patients with rheumatoid arthritis through medications like infliximab and etanercept." (PMID 31603905, 2019). "The inhibition of tumor necrosis factor (TNF) through the use of either antibodies or soluble receptors is a highly effective strategy for the clinical control of chronic inflammatory conditions such as rheumatoid arthritis." (PMID 31877657, 2019). "Cluster 10 contains rheumatoid arthritis and TNF signaling pathway." (PMID 31739287, 2019). "This implies that interference with the innate immune system with medicinal drugs, such as the IgLC-binding peptide modeled here, should be effective equally conditionally when other targets are chosen, such as TNF (an effective target in the treatment of rheumatoid arthritis or one of the MMPs." (PMID 32117197, 2019). "Furthermore, data from a meta-analysis study, suggests that the use of anti-cytokine therapies such as anti-TNF, improves depressive symptoms in patients being treated for chronic inflammatory diseases including rheumatoid arthritis." (PMID 31244825, 2019). "We determined whether rheumatoid factor (RF) and anti-cyclic citrullinated peptide antibody (ACPA) can predict remission or severe disability in rheumatoid arthritis (RA) patients treated with anti-tumor necrosis factor (TNF) alpha drugs." (PMID 30702571, 2019). "The epileptogenesis process has been linked with the over-production of pro-inflammatory cytokines such as tumor necrosis factor (TNF)-α and interleukin (IL)-6 as demonstrated by increased susceptibility to seizures in inflammatory disorders such as colitis, pneumonia and rheumatoid arthritis." (PMID 30649643, 2019). "Besides others, TNF antagonists reduce IL-17 controlled inflammatory pathways, and thus, slow down joint destruction in rheumatoid arthritis, reduce psoriatic lesions, as well as resolve chronic intestinal inflammation and ulcerations in IBD." (PMID 31295952, 2019). "The first successful biologics-based therapy of rheumatoid arthritis patients was developed in the early 1990s by Marc Feldman and Ravinder Maini at the Charing Cross Hospital, London, UK and made use of antibodies neutralizing TNFα." (PMID 31694340, 2019).
rheumatoid arthritis (continued). "Anti-TNF therapy offers a targeted strategy different from that of non-specific immunosuppressive agents and has been considered an option for many chronic inflammatory diseases, such as rheumatoid arthritis, psoriasis, and inflammatory bowel disease." (PMID 30837977, 2019). "Etanercept is a TNF-α antagonist that has already been developed and approved for the treatment of rheumatoid arthritis and several rheumatic diseases, and treatment with etanercept suppressed systemic inflammation and local inflammation in the brains of LPS-treated rats." (PMID 31470812, 2019). "Nowadays, the anti-TNF based therapy is widely used and approved for the treatment of chronic inflammatory conditions as rheumatoid arthritis, polyarticular juvenile idiopathic arthritis, plaque psoriasis and psoriatic arthritis, ankylosing spondylitis and inflammatory bowel diseases." (PMID 31469834, 2019). "TNF-α neutralizing agents and inhibitors have being used extensively to treat inflammatory diseases such as Crohn’s disease (CD), psoriasis, psoriatic arthritis (PA), and rheumatoid arthritis (RA), which result from the excessive production of TNF-α in the body." (PMID 31089365, 2019). "TNF-α inhibitors suppress nuclear factor-kappaB (NF-кB) activity, but one study showed that adalimumab therapy was not effective on the NF-кB activity of lymphocytes in patients with rheumatoid arthritis." (PMID 31686457, 2019). "Since TLO B cells were also found in the synovium of inflamed joints, Rituximab (an anti-CD20 B-cell depleting antibody) might be an alternative therapy for treating rheumatoid arthritis, besides of TNF-α and IL-1 antagonist in clinic." (PMID 31921189, 2019). "Recently, biological products, such as anti-TNF-α neutralized antibody (etanercept, infliximab, and adalimumab, etc.,) and anti-IL-6 neutralized antibody (tocilizumab), which are drugs created by biotechnology, have been used for rheumatoid arthritis." (PMID 31847314, 2019). "TNF-α inhibitors were the second common group of drugs launched for rheumatoid arthritis, and these had a mean inflation-adjusted launch price of £898.53, though single examples of an interleukin (IL)-1 inhibitor, an inhibitor of T-cell co-stimulation and IL-6 inhibitors were priced even higher." (PMID 31061053, 2019). "Similarly, VNS has recently been reported to improve rheumatoid arthritis, another TNFα mediated disease." (PMID 32232080, 2018). "Similarly treatment of autoimmune diseases, such as rheumatoid arthritis, Crohn’s disease and psoriasis, with anti-TNF therapies have had successful outcomes." (PMID 30206422, 2018). "Similarly, severe side effects have also been reported in approved anti-TNF treatment strategies, such as rheumatoid arthritis patients reporting the development of neurological symptoms, including demyelinating lesions." (PMID 30206422, 2018). "KEGG pathway analysis revealed the TNF signalling pathway, Osteoclast differentiation, Chemokine signalling pathway, Cytokine -cytokine receptor interaction, Rheumatoid arthritis, Biosynthesis of amino acids, Biosynthesis of antibiotics and Glycine, serine and threonine metabolism." (PMID 29745857, 2018). "An anti-TNF therapy improved fatigue in rheumatoid arthritis patients." (PMID 30150620, 2018). "It stands to reason, therefore, that the TNF-α inhibitors used to treat rheumatoid arthritis could indeed induce a state of hypoglycemia following chronic use." (PMID 30914847, 2018). "Similarly, the administration of Lactobacillus casei 01 bacteria to patients with rheumatoid arthritis significantly decreased TNF-α." (PMID 30400570, 2018). "The activity of monomer [K6T]P8 was also tested in synovial fluids from rheumatoid arthritis patients that normally showed high levels of IL-15, and consequently of TNFα.Both P8 and [K6T]P8 peptides were able to inhibit TNFα secretion, with the latter endowed with greater efficacy." (PMID 30208640, 2018).
rheumatoid arthritis (continued). "However, the overexpression of TNF-α also been connected to many inflammatory and autoimmune diseases such as rheumatoid arthritis, inflammatory bowel disease, ankylosing spondylitis, and psoriasis." (PMID 30258443, 2018). "Data are sparse on the risk of infections compared with rheumatoid arthritis, but there appears to be no risk in the absence of TNF-inhibitor exposure." (PMID 29594122, 2018). "These may include application of the THP TNF-α binding motif as a replacement of monoclonal antibody (MoAb) therapy against TNF-α in the treatment of immune-mediated chronic inflammatory diseases such as rheumatoid arthritis." (PMID 29361765, 2018). "We report the case of a 75-year-old female with a history of rheumatoid arthritis on TNF-antagonist immunosuppressive therapy who initially presented to the hospital for management of back and leg pain and was ultimately diagnosed with bacterial meningitis secondary to Salmonella species infection." (PMID 29951326, 2018). "The top 25 significantly different pathways were selected, including pathways in cancer, the PI3K-Akt signaling pathway, Rap1 signaling pathway, TNF signaling pathway, focal adhesion, and some disease pathways such as rheumatoid arthritis, tuberculosis, Influenza A, and Toxoplasmosis." (PMID 29787599, 2018). "Treatment with anti-TNF-α (tumor necrosis factor), one of the pivotal cytokines, was introduced to clinical practice at the end of last century and revolutionized the treatment of rheumatoid arthritis (RA) as well as many other inflammatory conditions." (PMID 29895751, 2018). "Our results are in accordance with few previous studies that showed significant improvement of insulin sensitivity after anti-TNF therapy in patients with rheumatoid arthritis, psoriasis, and ankylosing spondylitis, especially in subgroups with higher insulin resistance." (PMID 29576769, 2018). "These drugs block TNFα from interacting with its receptors and have enabled the development of breakthrough therapies for the treatment of several autoimmune inflammatory diseases, including rheumatoid arthritis, Crohn’s disease, and psoriatic arthritis." (PMID 29518978, 2018). "However, to date, only in small case series preliminary clinical improvement has been shown with rituximab therapy for AA amyloidosis secondary to rheumatoid arthritis that is refractory to anti-TNF-α therapy." (PMID 30400666, 2018). "In addition, TNF-α and IL-1β can trigger NF-κB activation in rheumatoid arthritis and infectious diseases." (PMID 29743895, 2018). "There is a perception that etanercept has a lower risk of serious infection than other biologics based on lower rates of tuberculosis, extrapolation from the rheumatoid arthritis literature, and the general assumption that a less efficacious tumor necrosis factor inhibitors would be safer." (PMID 29054603, 2018). "Clinical trials have shown combinations of anti–tumor necrosis factor biologicals plus methotrexate (MTX) are more effective treatments for rheumatoid arthritis than biological monotherapies, based, in part, on the assumption that MTX reduces the immunogenicity of biologicals." (PMID 29879987, 2018). "In rheumatoid arthritis, resistin has been shown to accumulate within inflamed joints, and to correlate with the degree of inflammation and the expression of inflammatory cytokines including TNF-α, IL-1β and IL-6." (PMID 28642544, 2017). "The TNFα level in the synovial fluid of rheumatoid arthritis patients is around 300 pg/ml." (PMID 28542363, 2017). "In rheumatoid arthritis, IL-6 stimulates the production of inflammatory cytokines by T and B lymphoid cells, promotes the maturation and differentiation of B cells, and enhances the effects of IL-1β and TNFα." (PMID 28953986, 2017).
rheumatoid arthritis (continued). "In this light, a phase II multi-center trial in rheumatoid arthritis resistant to anti-TNF-α antibody treatment showed promising results – patients treated with a TNF-kinoid not only developed neutralizing antibodies, but also had a trend towards improved clinical symptoms." (PMID 28942732, 2017). "For example, treatment of rheumatoid arthritis, may consist of blocking the effect of TNF-α using monoclonal antibodies such as infliximab, etanercept or adalimumab." (PMID 28895912, 2017). "TNFα induces proliferation of synovial fibroblasts derived from rheumatoid arthritis; however, it is unknown whether TNFα promotes proliferation of synovial MSCs." (PMID 28542363, 2017). "In fact, enhanced TNF production and TNF receptor 1 (TNFR1) signalling is associated with macrophage accumulation and inflammatory cytokine production in common autoimmune pathologies, such as Crohn's disease, rheumatoid arthritis and psoriasis." (PMID 28197335, 2017). "It is also involved in numerous pathological conditions and autoimmune disorders such as rheumatoid arthritis, lupus, psoriasis and atherosclerosis and there is now considerable evidence for successful use of TNFα blockers for the treatment of certain chronic inflammatory conditions." (PMID 28287124, 2017). "The TNF-α mediated signaling pathway has been extensively studied and several inhibitors or monoclonal-antibodies have been successfully used for the treatment of rheumatoid arthritis and inflammatory bowel disease." (PMID 29137272, 2017). "Although TNF-α inhibitors can control joint symptoms of rheumatoid arthritis, they may induce rheumatoid meningitis." (PMID 28286682, 2017). "Although both rheumatoid factor (RF) and anticyclic citrullinated peptide antibodies (anti-CCP) are useful for diagnosing rheumatoid arthritis (RA), the impact of these autoantibodies on the efficacy of tumor necrosis factor (TNF) inhibitors has been controversial." (PMID 28865493, 2017). "To expand our tissue target engagement analysis beyond skin samples, we evaluated RIPK1 target engagement in colon and synovial tissues, as these tissues are the major sites of inflammation in TNF‐dependent diseases such as ulcerative colitis and rheumatoid arthritis, respectively." (PMID 29226625, 2017). "Both TNF-α and interleukin-6 (IL-6) play major roles in the pathogenesis of rheumatoid arthritis." (PMID 29140972, 2017). "Specific targeting of immune processes has become possible with biological drugs, some of which have proven to be extremely efficent in controling autoimmune diseases such as anti-TNF-α in rheumatoid arthritis and Crohn’s disease or anti-CD20 in rheumatoid arthritis and ANCA vasculitis." (PMID 28584258, 2017). "Therefore this research was designed to determine and compare the TNF-α level in saliva among patients with Rheumatoid arthritis (RA), chronic periodontitis, and healthy control subjects." (PMID 28061876, 2017). "TNF is a pro-inflammatory cytokine that represents a critical mediator of the autoimmune process, playing a key role in several inflammatory diseases, including rheumatoid arthritis (RA), ulcerative colitis, and Crohn’s disease." (PMID 28824615, 2017). "Tumor necrosis factor-alpha (TNF-α) blockade is an effective treatment for rheumatoid arthritis (RA) and other inflammatory diseases, but in patients, it is associated with reduced resistance to the infectious agents Mycobacterium tuberculosis and Listeria monocytogenes, among others." (PMID 29184553, 2017). "Blockade of TNF-α activities with monoclonal antibodies (e.g. Infliximab, Adalimumab) as well as a receptor-immunoglobulin fusion protein (e.g. Etanercept) significantly improved clinical outcomes, in particular, rheumatoid arthritis." (PMID 27658047, 2016). "Etanercept is a TNF-α inhibitor originally used in the treatment of rheumatoid arthritis (RA)." (PMID 27054030, 2016).
rheumatoid arthritis (continued). "IL-21 could stimulate the expression of TNF-α in fibroblasts as it was shown in T cells during Rheumatoid arthritis." (PMID 26772733, 2016). "In addition to psoriasis treatment, anti-TNF-α Mabs have been used for treatment of other immune-mediated inflammatory diseases including rheumatoid arthritis, Crohn’s disease, ankylosing spondylitis, and ulcerative colitis." (PMID 27415000, 2016). "The study included 11,642 patients with rheumatoid arthritis – 2,241 of these started on anti-TNF drugs (+/-DMARD) and 9,401 patients started on DMARD – and 1,251 patients with ankylosing spondylitis – 976 of them were started on anti-TNF drugs (+/-DMARD) and 275 were started on DMARD." (PMID 27556964, 2016). "On the other hand, treatment with anti-TNF-α compounds improves cognitive function in patients with rheumatoid arthritis or sarcoidosis, indicating that it may be also beneficial if administered after establishment of cognitive impairment." (PMID 27623772, 2016). "Another example of the role of cytokines in chronic diseases can be found between TNF-α and rheumatoid arthritis, where anti-TNF-α antibodies were added to in vitro cultures of cells from diseased joints and inhibited the production of IL-1β and other cytokines." (PMID 27294919, 2016). "Additionally, Maxwell and colleagues demonstrated that the GA genotype at TNF-α -238 was associated with a poorer response to infliximab, an anti-TNF agent in the treatment of rheumatoid arthritis." (PMID 26572151, 2016). "Once tolerance is lost, increasing levels of inflammatory cytokines like TNF-α in the preclinical phase of rheumatoid arthritis may drive both joint and lung inflammation." (PMID 27450561, 2016). "Adalimumab (Humira®, Human Monoclonal Antibody in Rheumatoid Arthritis) is a human monoclonal TNF-α antibody used to threat rheumatoid arthritis, juvenile idiopathic arthritis, psoriatic arthritis, ankylosing spondylitis, plaque psoriasis, and Chron's disease in case of other drugs' failure." (PMID 27088019, 2016). "The lung has increased citrullination and TNF-α levels are high in rheumatoid arthritis; however, it is unknown if TNF-α can induce lung protein citrullination." (PMID 27450561, 2016). "In this regard, in patients with severe rheumatoid arthritis undergoing periodical treatment with anti-TNF-α-therapy and ongoing disease activity, low adiponectin levels clustered with metabolic syndrome features that reportedly contribute to atherogenesis in rheumatoid arthritis." (PMID 27293954, 2016). "Similarly, CoQ10 has also been observed to inhibit the expression of IL-6, TNF-α and NF-κB, an anti-inflammatory effect mediated via gene expression modification or antioxidant/radical-scavenging activity in Rheumatoid Arthritis Patients33." (PMID 27452860, 2016). "Anti-TNF drugs have been widely used in rheumatoid arthritis (RA) for more than 15 years." (PMID 26932562, 2016). "On the other hand, ROS could be generated by rheumatoid synovial cells via the nicotinamide adenine dinucleotide phosphate (NADPH) oxidase system (Nox), during exposure to two major rheumatoid arthritis (RA) cytokines, interleukin-1β (IL-1β) and TNF-α." (PMID 26770659, 2016). "In the present study, we show that overexpression of TNF-α, a major pathologic cytokine in rheumatoid arthritis, induces murine lung citrullination providing evidence for a pathway by which lung citrullination may be induced in human disease." (PMID 27450561, 2016). "TNF inhibitors (TNFi) has been advantageous for many individuals with rheumatoid arthritis (RA)." (PMID 27643491, 2016). "Moreover, inflammatory mediators such as prostaglandin E2 and inflammatory cytokines (TNF-α, Il-6) have been shown to exacerbate the related pain and decrease in mobility or physical activity in patients with rheumatoid arthritis and other joint diseases." (PMID 27333300, 2016).